TNF (tumor necrosis factor)
Diseases named in the same sentence as TNF in open-access papers (continued):
Sharing a sentence is not in itself a finding about the gene and the disease.
COVID-19 (continued). "The high expression levels of IL-6, TNF-α, and IL-10 may have led to cytokine storms in the neonates of mothers with COVID-19 because the relationship of those cytokines with the event has already been demonstrated in other studies." (PMID 36979888, 2023). "The TNFα/IL-10 radio, an indication of the balance between key pro- to anti-inflammatory levels, was also reduced to a similar level in severe, critical COVID-19, and non-COVID-19 critical patients." (PMID 36509969, 2023). "The TNF inhibitor, adalimumab, has also been used for the inflammatory phase of COVID-19." (PMID 37187644, 2023). "However, even 2–3 months after recovering from COVID-19, alterations in the levels of both pro-inflammatory cytokines, such as IL-1β, IL-6, TNFα, and the anti-inflammatory cytokine IL-10, have been observed in semen." (PMID 37958725, 2023). "This RCT has shown that the administration of potassium canrenoate to patients with COVID-19-induced pneumonia may be associated with significant changes in certain inflammatory markers (interleukin-6, CD3%, TNF-α), potentially related to pulmonary fibrosis." (PMID 37762549, 2023). "After the second dose of the COVID-19 vaccine, these cytokines also induced TNF-α and IL-6." (PMID 37049424, 2023). "In patients already infected with SARS-Cov-2, concomitant heart failure may deteriorate rapidly, it is reasonable to avoid anti-TNF therapy in all heart failure level patients who are suffering from COVID-19." (PMID 38029150, 2023). "The cytokine storm phenomenon is an increase in pro-inflammatory cytokine levels in the serum, such as IL-2, IL-6 and IL-1β, IL-17, IL-8, G-CSF, GM-CSF, IP10, MCP1, MIP1α (also known as CCL3), and TNF, and causes acute respiratory distress syndrome (ARDS) in severe COVID-19 cases." (PMID 37626992, 2023). "Interestingly, hospitalization rates were lower in COVID-19-infected RA patients who received therapy with TNF inhibitors." (PMID 37163438, 2023). "Indeed, IL-6, IL-1β, and tumor necrosis factor alpha (TNF-α) were found to be significantly elevated in COVID-19 patients." (PMID 37762435, 2023). "The regulation of inflammatory mediators, such as TNF-α, IL-6, IL-1β, and leukotriene B4, could play a crucial role in suppressing inflammatory diseases such as COVID-19." (PMID 36611603, 2023). "The systemic cytokine profiles observed in patients with severe COVID-19 show similarity to those observed in activated macrophages, with increased production of IL-6 and IL-7, tumor necrosis factor (TNF), and the inflammatory chemokine CC–chemokine ligands CCL2 and CCL3." (PMID 37892134, 2023). "In a cohort study of 50 patients, severe COVID-19 was associated with impaired function of monocytes and dysregulation of type 1 interferon (IFN-1) which can lead to a higher viral load and dysregulated TNF-alpha and IL-6 systemic response." (PMID 37593250, 2023). "However, given the results of studies demonstrating the adverse effects of excess TNF-α in COVID-19, these reports should be approached with caution." (PMID 37376562, 2023). "Finally, monocytes from convalescent COVID-19 patients demonstrate significantly decreased TNF-α and IL-6 expression in response to LPS stimulation compared to control subjects." (PMID 38250080, 2023). "We treated THP-1 macrophages with purified S1 protein to evaluate the expression of the pro-inflammatory cytokines TNF-α, CXCL10, and IFN-γ due to their association with hyperinflammation in SARS and COVID-19 patients, as well as the antiviral cytokine IFN-β, since it restricts SARS-CoV-2 infection." (PMID 36992463, 2023). "Similarly, a study found that IL-6 and TNF-α elevation was sustained in subjects that experienced symptoms at approximately 120 days following COVID-19." (PMID 37565145, 2023). "Furthermore, higher levels of TNF-alpha were observed in patients with severe/critical than mild or moderate courses of COVID-19." (PMID 37753372, 2023).
COVID-19 (continued). "Furthermore, the higher levels of IL-1β, IL6, IL-12p70, IL-17A, TNF-α, and IFN-γ are consistent with the inflammatory profile of COVID-19-associated lung injury." (PMID 38067158, 2023). "TNF-α serum levels were noticeably greater in COVID-19 patients than in the healthy group." (PMID 37240319, 2023). "The release of TNF-α through ADAM-17 is essential to COVID-19 pathogenesis." (PMID 37476705, 2023). "In addition, this review also proposes the potential of TNF-α as a biomarker for the prognosis of severe COVID-19 and its related complications and as a molecular target for anti-TNF-α therapy." (PMID 37047115, 2023). "Results from the hamster challenge study demonstrated a strong anti-inflammatory potential of A64, as the mRNA expression of inflammatory cytokines such as IL-6, IL-17A, and TNF-α (all of which have been strongly correlated with COVID-19 severity) was significantly reduced." (PMID 37765142, 2023). "In line with our findings, several reports described the overproduction of IL-6, TNF-α, and IL-1β, leukopenia and coagulopathy, marked by platelet activation and high D-dimer levels, accounting for the development of the more severe forms of the COVID-19." (PMID 37283924, 2023). "One study found elevated levels of the proinflammatory cytokine TNF-α in the olfactory epithelium of patients with COVID-19, suggesting that the direct inflammation of the olfactory epithelium could play a role in acute olfactory loss." (PMID 37175768, 2023). "In conclusion, although other studies should be considered to confirm these new data, this study allows us to suggest that a specific subset of TNF-α-producing NK cells could be involved in an immunopathological process leading to fatal forms of COVID-19." (PMID 37342247, 2023). "Also, the cytokine storm, a feature of the more severe forms of COVID-19, is reflected in a sharp increase in interleukin 10 (IL-10) and TNF-α serum levels, which would depend on the expression of the respective genes." (PMID 36928185, 2023). "Hyperinflammation is a hallmark of COVID-19 and is characterized by high levels of circulating proinflammatory cytokines, including interleukin-6 (IL-6), interferon-γ (IFN-γ), IL-1β, tumor necrosis factor (TNF), acute phase reactants, and ferritin." (PMID 38022199, 2023). "Both GA/18β doses modulated inflammatory response by reducing mainly IL-17A expression, which in turn kept IL-1β, IL-6, IL-8 and TNF-α interleukins unchanged, indicating significant modulation of key interleukin levels to prevent exacerbation of the immune response in COVID-19 patients." (PMID 38283346, 2023). "Nevertheless, overall data supported the hypothesis that high IL-1β, IL-6, and TNF-α in the same patient play a role in COVID-19 and periodontitis pathogenicity independently." (PMID 37106750, 2023). "Moreover, this cytokine storm also has an impact on the adaptive immune response, since the low expression of HLA-DR induced by high concentrations of IL-6 and TNF-α leads to a pronounced lymphopenia in severe COVID-19 cases." (PMID 37153606, 2023). "Although there are significant differences in terms of age, co-morbidities, and blood parameters, multivariate analysis still showed that the expression of MPO, ADA, CCL22, TNFα, and IL-6 mRNA in nasopharyngeal specimens is higher in COVID-19 patients when compared with the control group." (PMID 36482706, 2023). "In addition, several of the elevated inflammatory markers in patients with COVID-19, e.g., interleukin-6 (IL-6), tumor necrosis factor (TNF), and ferritin have been found to correlate positively with pCRP levels." (PMID 37724104, 2023). "The tumor necrosis factor (TNF-α), IL-6, and IL-10 concentrations are the most important mediators of cytokine storm formation, and their levels clearly distinguish mild from severe cases of COVID-19 and are associated with poor prognosis of the disease." (PMID 37759873, 2023).
COVID-19 (continued). "TNF-α production is elevated in COVID-19 patients, which disrupts the insulin signaling pathway." (PMID 37187644, 2023). "Results showed that IL-10 alone or in combination with IL23 and TNF-α are strongly linked with non-survivors in COVID-19 patients." (PMID 37283736, 2023). "Furthermore, the production of TNF-a is significantly increased in the CD56Bright NK cells of COVID-19 patients with a severe form (WT-S) at the two time-points (Pt1 and Pt2) compared to healthy donors." (PMID 37342247, 2023). "Also, acute COVID-19 children had significantly elevated levels of cytokines, IFNγ, IL-2, TNFα, IFNβ, IL-6, IL-12, IL-17A and Granulocyte-Colony Stimulating Factors G-CSF in comparison to control children." (PMID 37013538, 2023). "In addition to elevated IL-10 levels, TNF-α and IL-23 were also increased in serum of COVID-19 patients and correlated positively with CRP levels." (PMID 37283736, 2023). "TNF-α and IL-6-mediated CRS causes significant acute respiratory distress in COVID-19 patients." (PMID 36817449, 2023). "Additionally, in COVID-19 patients, serum levels of IL-6, TNF-α, IL-8, and IL-10 were negatively correlated with lymphocyte counts." (PMID 37654571, 2023). "Increased levels of cytokines and chemokines, particularly IL-6, IL-8, and tumor necrosis factor, along with lymphopenia and immune cell infiltration in affected organs, are known to contribute to the severity of COVID-19 and the accompanying hyper-inflammatory responses." (PMID 38136554, 2023). "Specifically, the Kyoto Encyclopedia of Genes and Genomes (KEGG) signaling pathway analysis showed that coronavirus disease-COVID-19, chemokine signaling pathway, TNF signaling pathway, IL-17 signaling pathway, influenza A and PD − L1 expression and PD − 1 checkpoint pathway in cancer were enriched." (PMID 37853397, 2023). "However, SARS-CoV-2 infection has been shown to suppress type I IFN antiviral responses (e.g., IFN-α and IFN-β) and elevate the production of inflammatory cytokines (e.g., IL-1β, IL-6, and TNF-α) in blood and lung samples from COVID-19 patients." (PMID 36883057, 2023). "Apart from periodontitis and COVID-19, local (salivary) and systemic (serum) TNF-α/IL-6/IL-1β levels also increased in other inflammatory conditions, such as chronic oral erosive lesions and ulcers, and these cytokine levels were inversely proportional to the IL-10 that regulated epithelial healing." (PMID 37106750, 2023). "This demonstrates the importance of TNF-α in the progression of COVID-19." (PMID 37047115, 2023). "However, this approach will require additional future study because studies have demonstrated that COVID-19 patients receiving TNF blockers showed a lower probability of hospitalization." (PMID 36936055, 2023). "In contrast, severe COVID-19 includes sustained expression of these markers with additional signatures including IL-6, IL-10, IL-18, IL-23, TNF, and eotaxin among others suggesting that specific timing and failure to resolve inflammatory responses are important factors in disease progression." (PMID 37491352, 2023). "Therefore, employing anti-TNF-α agents can be included in the treatment regimen that deals with the imbalance of immune response in COVID-19 and PACS." (PMID 37047115, 2023). "They found that none of the cytokines except TNF-α was associated with COVID-19 severity and pulmonary fibrosis." (PMID 37649897, 2023). "Anti-cytokine drugs, such asIL-6 receptor inhibitors and TNF-α inhibitors, require more in-depth research to reach a consensus about the best timing of these therapies when administering the COVID-19 vaccine, although preliminary data suggest they minimally hamper vaccine-induced immunogenicity." (PMID 38140217, 2023). "In contrast, LPS treatment caused a different change and down-regulated COVID-19 and Shigellosis, while the immune pathways that were activated after TNFα treatment did not change significantly." (PMID 37566046, 2023).
COVID-19 (continued). "However, TNF-α levels were significantly higher in COVID-19 and bacterial pneumonia groups compared to healthy controls (P<0.000)." (PMID 38585537, 2023). "As such, upregulation of IL-6 and TNF-α are core components of the cytokine storm in COVID-19." (PMID 36769623, 2023). "In COVID-19, neutrophils contribute to disease pathogenesis by producing pro-inflammatory cytokines like TNF-α and IL-6 that contribute to lung-centric and systemic cytokine storms and the chemokine CXCL8 to promote further neutrophil recruitment and augment inflammation." (PMID 38139412, 2023). "﻿To date, therapies targeting TNF-α have not been associated with adverse outcomes in IBD patients with COVID-19." (PMID 36698148, 2023). "However, significantly higher levels of IL-1β, TNF and IFNγ were found in semen from patients recovered from mild and/or severe COVID-19 with respect to control individuals (p < 0.05, p < 0.05 and p < 0.001, respectively)." (PMID 37497433, 2023). "IL-6 and TNF can contribute to the cytokine storm in COVID-19 patients." (PMID 37515272, 2023). "Patients in stage IV of COVID-19 had significantly higher serum level of pro-inflammatory cytokines IL-1β (p = 0.001), TNF-α (p = 0.012) and IL-12 (p = 0.001) as well as immunosuppressive IL-10 (p = 0.001) compared to the patients in less severe stages of disease." (PMID 36702907, 2023). "Considering that immunity and inflammatory responses are closely associated with the clinical manifestations of COVID-19 and outcomes, the levels of peripheral CD3+, CD4+, and CD8+ T cells as well as the levels of TNF-α, IL-6, and IL-10 were also determined in this study." (PMID 38249419, 2023). "However, early markedly downregulated FcεR1 gene expression observed in Moderate/Severe COVID-19 suggests an inappropriate response, which is further supported by the down regulated targets such as TNF, PTGS2 and IL-1B." (PMID 37261339, 2023). "The top five commonly enriched KEGG pathways (TNF signaling, IL-17 signaling, NF-kappa B signaling, NOD-like receptor signaling and Cytokine-cytokine receptor interaction pathways) are also significantly associated with COVID-19 and IPF diseases." (PMID 36949176, 2023). "Similarly, inflammatory mediators IL-6 and TNFα also contribute to myocardial remodeling and worse outcomes in COVID-19." (PMID 37568870, 2023). "Inflammatory cell death induced by TNF and IFN-γ signaling has been linked to COVID-19 mortality." (PMID 37327781, 2023). "A possible explanation could be the inhibition of severe systemic inflammatory reactions in the context of COVID-19 by anti-TNF drugs." (PMID 37766088, 2023). "As attenuated response to COVID-19 vaccines in patients treated with anti-TNFα was reported in other chronic inflammatory diseases, our results may have important clinical implications in these conditions as well." (PMID 37515078, 2023). "Patterns of cytokine alterations in AP and COVID-19 were shown to be remarkably similar in a recent meta-analysis, with tumor necrosis factor-alpha (TNF-α), interleukin (IL)-6, IL-8, and IL-10 concentrations significantly higher in more severe forms than non-severe forms of the two diseases." (PMID 36834656, 2023). "The induction of a type I IFN response in conjunction with TNF is another intriguing aspect that may contribute to the immunopathology of both COVID-19 and CM." (PMID 37791071, 2023). "Moreover, inflammatory markers including C-reactive protein, ferritin, interleukin (IL)-6, IP-10, MCP1, MIP1A, TNF-α, and vWF all were elevated in COVID-19 patients." (PMID 37854057, 2023). "In summary, older COVID-19 patients may present CMV reactivation, which could aggravate the disease course, influencing IFN-α and TNF-α production and increasing the risk of in-hospital death in elderly octogenarian patients." (PMID 37047803, 2023).
COVID-19 (continued). "Moreover, IFN-γ, IL-12p70, and TNF-α were stimulated by most of the COVID-19 vaccines, indicating the activation of these cytokines by the viral proteins, particularly the S protein." (PMID 36901827, 2023). "It appears that the high and uncontrolled release of pro-inflammatory cytokines (such as IL-6, IL-1, TNF-⍺) in COVID-19, ie the cytokine storm, is one of the main mechanisms explaining the severity of the disease in elderly patients, causing acute respiratory distress syndrome and death." (PMID 37498909, 2023). "Additionally, prior studies have found higher levels of TNF in the blood and tissues of COVID-19 patients." (PMID 37124230, 2023). "The PPI network analysis exhibits that numerous genes, including IL-6, TNF-α, MAPK3, MAPK1, AKT1, mTOR, HIF1A, HSP90AA1, EGFR, CASP3, etc., are implicated in the pathogenicity of COVID-19 disease and also in the anti-COVID-19 effects of Meliae cortex’s key active phytonutrients." (PMID 36817449, 2023). "Moreover, the literature-based pathway analysis uncovered a set of specific genes, such as CALCA, ACE, SIRT1, TNF, IL6, CCL2, and others, that were found to mediate the association between OA and COVID-19." (PMID 38020136, 2023). "In addition to its persistent elevation in our post-COVID patients, we identified a positive correlation between TNFα plasma levels after discharge and acute COVID-19 disease severity score (p < 0.05)." (PMID 36844209, 2023). "Furthermore, to limit the replication and spread of SARS-CoV-2 in COVID-19 patients, TNF-α also promotes the influx of neutrophils to the respiratory tract." (PMID 37047115, 2023). "Indeed, many cytokines are transactivated via the NF-κB signaling pathway, including those implicated previously in the inflammatory storm that accompanies severe COVID-19, such as IL-1, IL-6, IL-8, TNF, and CXCL1033." (PMID 37225706, 2023). "However, most of the included studies indicated elevated serum pro-inflammatory cytokine (IL-1β, IL-6 and TNF-α) levels in diseases (COVID-19/periodontitis) compared to healthy controls included in the same study." (PMID 37106750, 2023). "Lipoxins (LXs) might reduce the inflammatory changes that occur due to activation of MAPK, mTOR, and NLPR3 inflammasome in COVID-19, reduce tumor necrosis factor-alpha and interferon-gamma secretion, block T cell migration and promote T cell apoptosis." (PMID 36825200, 2023). "Furthermore, prophylactic administration of ivermectin suppressed the expression of pro-inflammatory cytokines (IL-6 and TNF) reported to be increased in severe cases of COVID-19." (PMID 37185581, 2023). "Moreover, IFN-I response co-existed with the TNF-alpha/IL-1β-driven inflammation was observed in patients with severe COVID-19." (PMID 37753372, 2023). "Although TNFα has been shown in several studies to be a reliable predictor of mortality in COVID-19, we reckon that other mechanisms could be at play, including the main component of the so-called cytokine storm." (PMID 36829885, 2023). "In the prognosis of COVID-19, changes in the level of TNF-α in comparison to the baseline can be used to predict the disease progression and severity, whereas using TNF-α inhibitors or blockers to treat COVID-19 can prevent mortality in severe COVID-19 patients." (PMID 37047115, 2023). "It has been previously investigated that CRP can induce TNF-α and IL-23 production by monocytes, so the elevation of TNF-α and IL-23 in COVID-19 patients might be related to CRP-induced monocytes." (PMID 37283736, 2023). "Interestingly, the post- COVID-19 cohort presented lower IL-6, IFN-γ, and TNF-α production after cell culture incubation with pathogenic stimulus." (PMID 37753077, 2023). "A similar time-dependent increase has been reported for IL-6, IL-8, IL-1β, and TNF-α in COVID-19." (PMID 38069209, 2023). "The need for prophylaxis (e.g., antifungal, antituberculosis) before administering long-term steroids or anti-TNF drugs could also be a future topic of discussion in COVID-19 patients." (PMID 37397682, 2023).